CP (ceruloplasmin)
Diseases named in the same sentence as CP in open-access papers (continued):
Sharing a sentence is not in itself a finding about the gene and the disease.
Lupus (5 papers, 2017 to 2025). "The Renal Activity Index for Lupus (RAIL) consists of urine protein assessment of neutrophil gelatinase–associated lipocalin, kidney injury molecule-1, monocyte chemotactic protein 1, adiponectin, hemopexin, and ceruloplasmin, which non-invasively identifies lupus nephritis (LN)." (PMID 36715772, 2023). "Since PA28γ’s discovery in 1990 from systemic lupus erythematosus (SLE) patient serum, its functional role with the 20S CP has been heavily debated." (PMID 37759726, 2023).
nephrotic syndrome (5 papers, 2018 to 2025). A collection of symptoms that include severe edema, proteinuria, and hypoalbuminemia; it is indicative of renal dysfunction. "Serum ceruloplasmin was markedly reduced, confirming the diagnosis of WD with associated nephrotic syndrome." (PMID 40688890, 2025). "Investigations showed nephrotic range proteinuria, elevated liver enzymes, low serum ceruloplasmin, and Kayser-Fleischer rings, confirming a diagnosis of WD with associated nephrotic syndrome." (PMID 40688890, 2025). "Ceruloplasmin is an acute-phase reactive protein, which is often confounded by many other diseases, including decompensated liver failure, nephrotic syndrome, protein-losing enteropathy, and acquired copper deficiency." (PMID 36570465, 2022). "It is well known that CP levels decrease in some patients with the nephrotic syndrome, and it has been suggested that the low CP levels can result from CP loss in the urine." (PMID 29324775, 2018). "However, the presence of LN in the patient who presented with nephrotic syndrome led us to consider that the decreased ceruloplasmin levels may be related to significant protein loss due to LN, which was also a factor contributing to the delayed diagnosis." (PMID 38622515, 2024). "Of 324 patients with nephrotic syndrome, 37.7% of patients had CP <200 mg/L, 13.9% had CP <150 mg/L, and 2.2% had CP <100 mg/L." (PMID 29324775, 2018). "Our study confirmed that the mean CP level is significantly lower in patients with nephrotic syndrome than in those with other conditions." (PMID 29324775, 2018).
osteoporosis (5 papers, 2019 to 2025). A condition of reduced bone mass, with decreased cortical thickness and a decrease in the number and size of the trabeculae of cancellous bone (but normal chemical composition), resulting in increased fracture incidence. "A recent study showed that CP activity was significantly higher in patients with osteoporosis compared to healthy individuals." (PMID 31766436, 2019). "Additional studies are needed to validate whether serum CP levels may be involved in bone remodeling and eventually lead to the development of osteoporosis." (PMID 31766436, 2019). "Some of these proteins include Vitamin D Binding Protein (VDBP), ceruloplasmin (CP), and gelsolin (GSN), one of the proteins most frequently reported in patients with osteoporosis." (PMID 39062769, 2024). "In this study, the random forest model was used to screen out five key ferroptosis genes, including CP, HAMP, HMOX1, FLT3, and SLC2A3, and these 5 differentially expressed key ferroptosis genes were preliminarily verified in the osteoporosis model constructed." (PMID 38650009, 2024). "However, CP levels have never been investigated in osteoporosis patients." (PMID 31766436, 2019). "Among the identified proteins showing significant changes in expression between NOR, OS, and OP samples, serum levels of CP, GSN, NADPH 1, and SERPINC 1 were usually lower in osteopenia than in the osteoporosis group." (PMID 31766436, 2019).
Sepsis (5 papers, 2015 to 2024). Sepsis is defined as life-threatening organ dysfunction caused by a dysregulated host response to infection. "In their investigation, Julian Hackler and colleagues explored the significance of selenium (Se) and copper (Cu) levels, as well as the biomarkers selenoprotein P (SELENOP) and ceruloplasmin (CP), in identifying early-onset sepsis (EOS) in neonates." (PMID 39655034, 2024). "Furthermore, when we compared their cargo, it turned out that the blood plasma MPs do carry ceruloplasmin in homeostasis but its content increases significantly as sepsis progresses." (PMID 38008825, 2024). "Although drops in plasma levels are generally associated with liver malfunction, ceruloplasmin has not been linked specifically to sepsis progression prior to this study." (PMID 31568522, 2019). "Clinical trials confirmed that the serum ceruloplasmin levels may help in the diagnosis of sepsis." (PMID 26388860, 2015).
age-related macular degeneration (4 papers, 2013 to 2024). Age-related loss of vision in the central portion of the retina (macula), secondary to retinal degeneration. "In mice with targeted mutations in the iron-exporter ceruloplasmin, retinal iron overload occurs at an age-dependent rate, leading to degeneration of the retina that shares features with age-related macular degeneration (AMD)." (PMID 38858683, 2024). "CP is a documented actor in age-related macular degeneration." (PMID 30050429, 2018). "CP and HEPH are co-expressed in retina and combined loss lead to age-related macular degeneration (AMD)." (PMID 33917579, 2021).
bladder cancer (4 papers, 2020 to 2022). "Taken together, our findings support the possible involvement of high plasma ceruloplasmin level in increasing copper levels in the blood in bladder cancer patients." (PMID 32620920, 2020). "We previously discovered potential urine protein biomarkers indicating the occurrence of bladder cancer, including afamin, adiponectin, complement C4 gamma chain, apolipoprotein A-II precursor, ceruloplasmin, and prothrombin using multiplex reaction monitoring mass spectrometry (MRM-MS)." (PMID 36428492, 2022). "Western blots of plasma samples probed with the ceruloplasmin antibody exhibited the tendency observed in 2D-DIGE and showed reduced expression of the 140 kDa isoform in low grade bladder cancer patients when compared to healthy controls." (PMID 32620920, 2020). "Annexin-V FITC/Per CP staining showed that treatments of EGCG, DOX, and EGCG plus DOX, resulted in significant apoptosis induction efficacies in bladder cancer SW780 and T24 cells." (PMID 33425912, 2020).
C. perfringens infection (4 papers, 2019 to 2025). "Compared with the other three groups, C. perfringens infection induced the highest expression of TNF in the CB/CP group." (PMID 31681193, 2019). "Moreover, the findings underscore a coordinated effort of the host to mitigate the C. perfringens infection via activating immune (a.o., C3, CFH, MASP2, MBL2) and acute phase (CP, ORM, TF, ExFAB) related proteins." (PMID 40275387, 2025).
cardiomyopathy (4 papers, 2013 to 2024). A disease of the heart muscle or myocardium proper. "Among these, SAA and ceruloplasmin were higher in CHF cats compared to cats with preclinical cardiomyopathies." (PMID 32395893, 2020).
cervical cancer (4 papers, 2017 to 2024). A primary or metastatic malignant neoplasm involving the cervix. "In this regard, PEGylated liposomes have been prepared for the delivery of CP in cervical cancer therapy." (PMID 39346915, 2024). "In this respect, CD59 receptor targeted delivery of miRNA-1284 and CP-loaded liposomes for effective therapeutic efficacy against cervical cancer cells." (PMID 39346915, 2024). "Ceruloplasmin expression cannot be detected in normal squamous epithelium and endocervical glands, butits expression is increased in cervical cancer subtypes, including squamous cell carcinoma and adenocarcinoma." (PMID 34413268, 2021). "A rise in serum ceruloplasmin was observed in cervical cancer, and that rise was higher in later stages of cancer than in early stages." (PMID 28423673, 2017). "Furthermore, GO-silver nanoparticle nanocomposites and CP working together increase apoptosis and autophagy in human cervical cancer cells." (PMID 39346915, 2024).
dementia (4 papers, 2011 to 2025). Loss of intellectual abilities interfering with an individual's social and occupational functions. "Interestingly, this protein was down regulated in CSF of subjects with HIV dementia whereas it was up-regulated in plasma, suggesting that the CSF-to-plasma ratio of ceruloplasmin may be an important correlate of HIV-associated neurocognitive impairment." (PMID 22359561, 2012). "Serum CP and FT are widely recognized as inflammatory biomarkers, and both proteins serve as indicators of cellular damage in conditions such as AD, dementia, and AMD." (PMID 40650085, 2025).
endometritis (4 papers, 2016 to 2022). An acute or chronic, usually bacterial infectious process affecting the endometrium. "Diagnostic test characteristics of oxidative stress, ceruloplasmin, and neopterin parameters in healthy and she-camel with clinical endometritis." (PMID 36156882, 2022). "Correlation matrix between oxidative stress, ceruloplasmin, and neopterin biomarkers in healthy and she-camels with clinical endometritis." (PMID 36156882, 2022). "The present study showed that the clinical endometritis she-camels have remarkable changes in serum OS, CP, and NPT levels, whereas, we observed higher levels of these biomarkers in she-camel with CE than healthy controls." (PMID 36156882, 2022). "In conclusion, it was determined that ceruloplasmin levels increase significantly in the presence of endometritis and proportionate to the severity of endometritis." (PMID 27847413, 2016). "This study found that serum ceruloplasmin levels were significantly higher in cows with endometritis than in healthy cows (13.52±0.32 mg/dl) and that the ceruloplasmin level significantly increases as endometritis becomes more severe." (PMID 27847413, 2016). "Cutoff, sensitivity, and specificity values for the Hp, SAA, and ceruloplasmin levels determined as a result of the ROC analysis on healthy cows and those with endometritis (mild and moderate) are provided in Table-1." (PMID 27847413, 2016). "Lamand and Levieux reported that plasma ceruloplasmin levels were higher in sheep with uterine infections or inflammation than in healthy sheep." (PMID 27847413, 2016). "Hp, SAA, and ceruloplasmin levels were higher in cows with endometritis than in healthy cows (p=0.001), and the levels of these APPs increased as endometritis became more severe (p=0.001)." (PMID 27847413, 2016). "According to study results, SAA and ceruloplasmin concentrations were significantly higher in cows with endometritis than in healthy controls, and positively correlated with the severity of the endometritis, by confirming the utility of APPs as markers of endometritis in cows." (PMID 35268158, 2022). "Another study in cows, focusing on the evaluation of acute-phase proteins in the blood in relation to endometritis during 28–32 d pp, showed a significant increase in Hp, SAA, and ceruloplasmin in the presence of endometritis with levels proportionate to the severity of the disease." (PMID 36139263, 2022). "The aim of this study is to determine serum ceruloplasmin levels in cows with endometritis of varying degrees of severity and to establish whether or not there is a correlation between acute phase protein (APP) levels and biochemical parameters." (PMID 27847413, 2016). "The aim of this study was to identify changes in serum ceruloplasmin levels in cows with endometritis based on the degree of severity and to establish whether or not serum ceruloplasmin levels can be used in the diagnosis of endometritis as an alternative to Hp and SAA levels." (PMID 27847413, 2016). "Serum ceruloplasmin levels in cows with endometritis which were not known before were significantly higher in the presence of endometritis, and the severity of endometritis plays an important role in this increase." (PMID 27847413, 2016). "Hp, SAA, and ceruloplasmin levels did not overlap in healthy cows and those with severe endometritis." (PMID 27847413, 2016). "The first was to determine whether or not ceruloplasmin levels can be used as an indicator in the diagnosis of endometritis." (PMID 27847413, 2016).
fibrosis (4 papers, 2013 to 2025). the formation of excess fibrous connective tissue in an organ or tissue in a reparative or reactive process. "In the present study, we used serum CP levels as a biomarker to identify CHB patients with fibrosis." (PMID 24282481, 2013). "To evaluate the direct role of FUS nuclear translocation in fibrosis, we used mice that carry a mutation in the FUS nuclear localization sequence (FUSR521G) and the cell-penetrating peptide CP-FUS-NLS that we previously showed inhibits FUS nuclear translocation in vitro." (PMID 38488009, 2024). "The patient presented as a 14.5-yr-old adolescent with chronically elevated aminotransferases, normal ceruloplasmin, and histologic examination consistent with NAFLD with advanced fibrosis." (PMID 30026388, 2018). "However, negative correlations were found between fibrosis stage and albumin, CHE, PLT, and CP (all P-values<0.05)." (PMID 24282481, 2013).
hyperglycaemia (4 papers, 2015 to 2025). "However, these CP values can be confounded by hyperglycaemia as evident by the high (>200 pmol/L) and/or similar CP levels between progressors and non‐progressors for glycaemic deterioration in our cohort." (PMID 35174618, 2022). "There are at least two side effects of CP-based therapy: 1) CP could stimulate ERK activation and thus might promote cancer cell survival; 2) Hyperglycemia is one of the most highly occurred adverse events in clinical trials, which might benefit tumor cell growth." (PMID 26287334, 2015).
ischemic stroke (4 papers, 2011 to 2025). A stroke disorder caused by obstruction of blood flow to the brain, due to thrombotic (local blood clot formation) or embolic (due to a blood clot or other material traveling from another site) event. "Lai showed that elevated CP activity, not increased CP concentration, was associated with an increased risk of ischaemic stroke." (PMID 39936900, 2025).
kidney cancer (4 papers, 2012 to 2024). Primary or metastatic malignant neoplasm involving the kidney. "Similar results were seen in a phase II trial with advanced kidney cancer patients in which the anti-tumor effects of TM (decreased vascularity and tumor mass) were associated with lower serum copper and ceruloplasmin levels." (PMID 23251472, 2012). "Furthermore, the blood levels of such proteins as alpha-1-acid glycoprotein 2 (P19652) (р = 0.02) and ceruloplasmin (P00450) (р = 0.04) in patients in the kidney disease and kidney cancer groups were also simultaneously increased 1.4-fold and 1.3-fold, respectively." (PMID 39896931, 2024).
leukopenia (4 papers, 2010 to 2024). "In addition, gastric problems were noted in the majority of patients and laboratory abnormalities included leukopenia, slightly elevated serum transaminases, low serum copper and ceruloplasmin, and high alkaline phosphatase." (PMID 27231034, 2016).
lupus nephritis (4 papers, 2022 to 2024). Glomerulonephritis in the context of systemic lupus erythematosus. "The Renal Activity Index for Lupus Nephritis (RAIL), comprising six urinary proteins—NGAL, MCP-1, ceruloplasmin, adiponectin, hemopexin, and Kim1—serves as an ideal predictor of renal activity in LN among children." (PMID 39104393, 2024). "We now add four additional biomarkers of importance to lupus nephritis research: MCP-1, Adiponectin, Hemopexin and Ceruloplasmin." (PMID 35967565, 2022).
malnutrition (4 papers, 2008 to 2025). Inadequate nutrition resulting from poor diet, malabsorption, or abnormal nutrient distribution. "The Study showed that the risk of malnutrition was higher for CP+/-L infants born with a low birth weight." (PMID 28086763, 2017). "As the methods of assisted feeding were not assessed in this study, another study may therefore be required to assess the most applicable feeding method to assist infants born with CP+/-L in our setting in order to reduce the rate of malnutrition." (PMID 28086763, 2017). "The combination of lack of provision of nutritional information following the delivery of a CP+/-L infant, number of feeds less than 10 received per day by the CP+/-L infant and low birth weight was found to be the greatest predictor of malnutrition among CP+/-L infants." (PMID 28086763, 2017). "CP+/-L infants born in Uganda suffer a high-burden of malnutrition." (PMID 28086763, 2017). "The low serum copper level or serum ceruloplasmin level may occur in protein energy malnutrition but the presence of pili torti, characteristics hair phenotype, asymptomatic huge bilateral subdural hematoma, and characteristics cerebral vasculature are not found in malnutrition." (PMID 18801184, 2008).
non-small cell lung carcinoma (4 papers, 2017 to 2024). A group of at least three distinct histological types of lung cancer, including non-small cell squamous cell carcinoma, adenocarcinoma, and large cell carcinoma. "By immunoblot, Q-PCR, and immunohistochemical (IHC) staining, we found that ceruloplasmin, lipocalin-2, and periostin are not only upregulated in the lung tumor tissues of Gprc5a-ko mice, but also in human non-small cell lung cancer (NSCLC)." (PMID 28088789, 2017). "CHST11 may promote the metastasis of non-small cell lung cancer cells through dysregulation of ceruloplasmin and intracellular iron balance." (PMID 38565604, 2024). "However, in non-small cell lung cancer (NSCLC) with KRAS mutation and LKB1 deletion, the expression of carbamoyl phosphate synthase (CPS) 1 increases; this change leads to an increase in the CP, which moves from mitochondria to the cytoplasm." (PMID 33926551, 2021).
parasitic infection (4 papers, 2012 to 2025). "The current knowledge on complement evasion strategies used by T. cruzi highlights the importance of the LP, AP, and CP as crucial components in the first line of defense against this parasitic infection." (PMID 28473804, 2017). "Since DEC had been administered only to the CP Ag− group and the presence of other parasitic infections not examined, the effect of treatment with DEC as well as the influence of other parasitic infections could not be ascertained in this study." (PMID 22685406, 2012).
psoriasis (4 papers, 2021 to 2022). An autoimmune condition characterized by red, well-delineated plaques with silvery scales that are usually on the extensor surfaces and scalp. "Although studies on calcineurin inhibitor (i.e., tacrolimus, pimecrolimus) use in NP are lacking, their use for NP associated with inflammatory skin diseases, such as AD and psoriasis, may be attempted based on experience with CP (Pereira and Ständer, 2017)." (PMID 34632036, 2021). "The levels of trace elements and acute phase proteins (Cu, Fe, transferrin, ceruloplasmin), although significantly altered in patients with psoriasis, do not seem to correlate with the severity or duration of the disease." (PMID 35204165, 2022).
tuberculosis (4 papers, 2022 to 2025). A chronic, recurrent infection caused by the bacterium Mycobacterium tuberculosis. "These include tuberculosis (ranked 9th), CP-CRE (ranked 17th), legionellosis (ranked 15th), salmonellosis (ranked 26th), and shigellosis (ranked 28th), all detecteble both in human excreta and wastewater." (PMID 37333521, 2023). "The present study aims to assess the serum ceruloplasmin-to-albumin ratio in patients with pulmonary tuberculosis (PTB), investigating its potential as a diagnostic and prognostic marker in TB therapy." (PMID 39006642, 2024). "Additionally, the study seeks to compare the serum ceruloplasmin-to-albumin ratio in patients with PTB before and after undergoing anti-tuberculosis treatment (ATT)." (PMID 39006642, 2024). "Furthermore, CASP8, APOA1, CP and INFG were all enriched in tuberculosis." (PMID 40083347, 2025).